MIR204 (microRNA 204)
Synonyms: hsa-mir-204; MIRN204; RDICC; miRNA204; mir-204
Gene: MicroRNA gene on chromosome 9 (70,809,975 to 70,810,084, reverse strand). Ensembl gene ENSG00000207935.
Gene Ontology:
Cellular component: RISC complex
Homologues: Orthologues: chimpanzee ptr-mir-204 (100% identical), macaque mml-mir-204 (100% identical), rat Mir204 (98% identical), pig ssc-mir-204 (95% identical), rabbit MIR204 (83% identical), tropical clawed frog xtr-mir-204-2 (75% identical), zebrafish mir204-1 (67% identical), dog MIR204 (62% identical), guinea pig MIR204 (62% identical), mouse Mir204 (62% identical). Paralogues in human: MIR211 (61% identical).
Diseases named in the same sentence as MIR204 in open-access papers:
MIR204 is named in the same sentence as 17 diseases in open-access papers, as found by Europe PMC text mining. Sharing a sentence is not in itself a finding about the gene and the disease. The quoted sentences say what the papers report.
iris coloboma (2 papers, 2020 to 2024). "One MIR204 SNV (rs767146880) that lies within the seed region (n.37C>T) has been linked with inherited retinal dystrophy and iris coloboma." (PMID 32070426, 2020). "In humans, mutation of TRPM3 underlies pediatric cataract with or without glaucoma and anterior segment defects, whereas mutation of MIR204 underlies retinal dystrophy and iris coloboma with or without cataract." (PMID 32070426, 2020). "Finally, mutation of the gene for micro-RNA 204 (MIR204), which is embedded within an intron of TRPM3, underlies autosomal dominant retinal dystrophy and iris coloboma with or without congenital cataract (RDICC)." (PMID 38334649, 2024).
Arthritis (1 paper, 2022). Inflammation of a joint. "Structure-specific recognition protein 1 (Ssrp1) knockdown exerts anti-arthritis effect in collagen-induced arthritis (CIA) Mir204/Mir211 double knockout (dKO) mice." (PMID 36511897, 2022). "Compared with WT mice with CIA induction, Mir204/Mir211 dKO mice with CIA induction showed much more severe paw swelling and increased arthritis score." (PMID 36511897, 2022).
autism (1 paper, 2014). Persistent deficits in social interaction and communication and interaction as well as a markedly restricted repertoire of activity and interest as well as repetitive patterns of behavior. "In the autism family, a paternal deletion of exons 1–9 that included MIR204 was shared by two affected sons and an unaffected daughter." (PMID 25090642, 2014).
cataract (1 paper, 2024). Partial or complete opacity of the crystalline lens of one or both eyes that decreases visual acuity and eventually results in blindness. "We note that hyper-mature cataracts have been reported in Mir204; Mir211-dKO mice at 10–15 months of age." (PMID 38334649, 2024).
medulloblastoma (1 paper, 2019). A malignant, invasive embryonal neoplasm arising from the cerebellum. "CpG island at the TRPM3/MIR204 promoter locus seems to be not methylated in Group 3 / Group 4 medulloblastomas based on the data from the Illumina 450 K array and bisulfite sequence analysis done on Group 3 medulloblastoma cell lines for the CpG island in the TRPM3/MIR204 promoter region." (PMID 30944042, 2019).
osteoarthritis (1 paper, 2022). A noninflammatory degenerative joint disease occurring chiefly in older persons, characterized by degeneration of the articular cartilage, hypertrophy of bone at the margins and changes in the synovial membrane. "It is known that Mir204/211 play an important role in protecting osteoarthritis development; however, the roles of Mir204/211 in RA disease have not been determined." (PMID 36511897, 2022). "We have previously reported that homologous miRNAs, Mir204 and Mir211, together protecting joint from osteoarthritis development." (PMID 36511897, 2022).
schizophrenia (1 paper, 2015). A major psychotic disorder characterized by abnormalities in the perception or expression of reality. "Thereby we found variant rs7861254 located near the MIR204 gene to be significantly associated with schizophrenia." (PMID 26714269, 2015).
tumor (2 papers, 2015 to 2022). "Several cancer-related studies have investigated the function of MIR204. miR-204-5p was shown to have a tumor-suppressor function through the negative regulation of cell migration and invasion." (PMID 26714269, 2015).
MIR204 also shares sentences with these, for which no sentence is quoted: breast carcinoma (1 paper); cancer (1); esophageal cancer (1); glaucoma (1); head and neck cancer (1); inflammation (1); ovarian carcinoma (1); Retinal dystrophy (1); rheumatoid arthritis (1).